INPP5F (inositol polyphosphate-5-phosphatase F)
Description:
Phosphoinositide phosphatase which catalyzes the hydrolysis of phosphatidylinositol 4-phosphate (1,2-diacyl-sn-glycero-3-phospho- (1D-myo-inositol 4-phosphate), PtdIns(4)P). May be functionally linked to OCRL, which converts phosphatidylinositol 4,5-bisphosphate (PtdIns(4,5)P2) to PtdIns, for a sequential dephosphorylation of (PtdIns(4,5)P2) at the 5 and 4 position of inositol, thus playing an important role in the endocytic recycling. Regulator of TF:TFRC and integrins recycling pathway, is also involved in cell migration mechanisms. Modulates AKT/GSK3B pathway by decreasing AKT and GSK3B phosphorylation. Negatively regulates STAT3 signaling pathway through inhibition of STAT3 phosphorylation and translocation to the nucleus. Functionally important modulator of cardiac myocyte size and of the cardiac response to stress (By similarity). May play a role as negative regulator of axon regeneration after central nervous system injuries (By similarity). May be involved in insulin granule docking at the plasma membrane of pancreatic cells, an essential step for insulin secretion.
Synonyms: hSAC2; KIAA0966; SAC2; MSTP007; MSTPO47
Tractability: PROTAC: its protein half-life has been measured.
Gene: Protein-coding gene on chromosome 10 (119,726,035 to 119,829,151, forward strand). Ensembl gene ENSG00000198825.
Subcellular location: Membrane, clathrin-coated pit; Early endosome; Recycling endosome
Subcellular location (Human Protein Atlas): Vesicles
Pathways (Reactome):
Metabolism: Synthesis of PIPs at the early endosome membrane
Gene Ontology:
Molecular function: phosphatidylinositol phosphate 4-phosphatase activity; phosphatidylinositol phosphate 5-phosphatase activity; protein binding; protein homodimerization activity; inositol monophosphate 4-phosphatase activity; phosphatase activity; phosphatidylinositol-4-phosphate phosphatase activity
Biological process: phosphatidylinositol dephosphorylation; positive regulation of receptor recycling; regulation of cell motility; regulation of endocytic recycling; cardiac muscle hypertrophy in response to stress; clathrin-dependent endocytosis; negative regulation of axon regeneration; phosphatidylinositol biosynthetic process; phosphatidylinositol catabolic process; adult locomotory behavior
Cellular component: clathrin-coated endocytic vesicle; clathrin-coated pit; early endosome; recycling endosome; early endosome membrane; axon; cytoplasm; dendrite; neuronal cell body
Genetic constraint (gnomAD): Loss-of-function variants: 64 observed, 93.34 expected, observed/expected ratio (o/e) 0.69, 90% interval 0.56 to 0.84. The upper end of that interval is the gene's LOEUF score, 0.84, which puts it in group 3 of 6, group 1 being the genes least tolerant of losing a copy. Missense variants: 997 observed, 1,104.4 expected, observed/expected ratio (o/e) 0.9, 90% interval 0.86 to 0.95. Synonymous variants: 410 observed, 392.13 expected, observed/expected ratio (o/e) 1.05, 90% interval 0.96 to 1.13.
Homologues: Orthologues: chimpanzee INPP5F (99% identical), macaque INPP5F (98% identical), pig INPP5F (94% identical), dog INPP5F (92% identical), mouse Inpp5f (91% identical), rat Inpp5f (90% identical), guinea pig INPP5F (89% identical), rabbit INPP5F (86% identical), tropical clawed frog inpp5f (74% identical), zebrafish inpp5f (72% identical), Drosophila melanogaster sp3 (35% identical), Caenorhabditis elegans sac-2 (25% identical), and 4 more. Paralogues in human: SYNJ2 (13% identical), INPP5D (12% identical), OCRL (12% identical), INPP5B (11% identical), SYNJ1 (11% identical), INPPL1 (11% identical), FIG4 (10% identical), INPP5J (10% identical), SACM1L (9% identical), INPP5E (7% identical), INPP5K (7% identical), SH2D1B (3% identical), and 1 more.
Diseases named in the same sentence as INPP5F in open-access papers:
INPP5F is named in the same sentence as 26 diseases in open-access papers, as found by Europe PMC text mining. Sharing a sentence is not in itself a finding about the gene and the disease. The quoted sentences say what the papers report.
cardiac hypertrophy (6 papers, 2014 to 2025). "This led to a dose-dependent restoration of downstream effector genes KLF4 and INPP5F, significantly improving cardiac hypertrophy parameters and alleviating myocardial hypertrophy." (PMID 40786032, 2025). "Treatment of mice overexpressing Hdac2 with TSA increases GSK3β and following INPP5f activity, which prevents cardiac hypertrophy." (PMID 35958418, 2022). "Through modulation of the AKT/mTOR pathway, palmatine reduced transcriptional levels of myocardial hypertrophy markers ANP and BNP, while inhibiting the hyperactivation of the HDAC2-KLF4/INPP5F pathway." (PMID 40786032, 2025). "In cardiac hypertrophy HDAC I downregulates the anti-hypertrophy gene expression, including Kruppel-like factor 4 (Klf4) and inositol-5 phosphatase f (Inpp5f), and promote the development of cardiac hypertrophy." (PMID 35958418, 2022). "Genes that suppress cardiac hypertrophy, including KLF4 and INPP5F, are potential therapeutic targets for cardiac hypertrophy." (PMID 35719043, 2022).
Parkinson disease (5 papers, 2022 to 2024). A progressive degenerative disorder of the central nervous system characterized by loss of dopamine producing neurons in the substantia nigra and the presence of Lewy bodies in the substantia nigra and locus coeruleus. "It is noteworthy that mutations in the IDR‐containing lipid phosphatases such as the PI 4−/5‐phosphatase Synaptojanin 1 and the PI 4‐phosphatase Sac2/INPP5F are also causally linked to Parkinsonism, implicating dysfunctional lipid metabolism in the disease." (PMID 37680133, 2023). "We nominated candidate genes in each locus and identified novel pathways potentially involved in Parkinson’s disease, such as the inositol phosphate biosynthetic pathway (INPP5F, IP6K2, ITPKB and PPIP5K2)." (PMID 37804111, 2024).
glioma (4 papers, 2014 to 2025). A benign or malignant brain and spinal cord tumor that arises from glial cells (astrocytes, oligodendrocytes, ependymal cells). "In addition, loss of INPP5F gene in gliomas is significantly correlated with lower overall patient survivals." (PMID 25476455, 2014). "In glioma, the gene INPP5F has been shown to reduce tumor progression, while its expression contributes to metastasis in colon cancer." (PMID 40391157, 2025). "A recent report suggests that INPP5F acts as a tumor suppressor in gliomas through a mechanism involving STAT3 pathway inhibition." (PMID 31796844, 2019). "To further investigate the tumor suppressor effect of INPP5F in gliomas, we analyzed the INPP5F gene expression and glioma patient survival data contained in the REMBRANDT dataset." (PMID 25476455, 2014). "INPP5F deletion is correlated with a decreased survival rate for glioma patients, and overexpressed INPP5F suppresses glioblastoma cell proliferation, GSCs' self-renewal, and gliomagenesis through inhibition of STAT3 pathway." (PMID 25476455, 2014). "Next, we generated constitutively INPP5F overexpressing and knockdown glioblastoma cell lines to investigate the biological role of INPP5F in gliomas tumorigenicity." (PMID 25476455, 2014). "Compared with controls, INPP5F gene expression is significantly decreased in 379 glioblastoma samples in TCGA, and in 545 all types of gliomas in REMBRANDT (both p<0.0001)." (PMID 25476455, 2014). "In this study, we analyzed TCGA and REMBRANDT databases and identified that INPP5F located in chromosome 10q26.11 is one of the highly altered glioma-related genes." (PMID 25476455, 2014). "Taken together, for the first time, our study identified a novel role of INPP5F as a tumor suppressor in glioma tumorgenicity." (PMID 25476455, 2014). "The expression of INPP5F is significantly suppressed in glioblastomas and all types of gliomas, which correlated with decreased survival rates in glioma patients, suggesting that INPP5F might be a tumor suppressor in glioma pathogenesis." (PMID 25476455, 2014). "When analyzed the correlation between INPP5F in clinical samples and survivals of glioma patients, we found that consistent our experimental data, INPP5F expression is highly correlated with patient survivals, and these clinical relevance is supported by in vivo experiments." (PMID 25476455, 2014). "Although the retrospective data cannot determine whether INPP5F could be an independent predictor of survival, these data that INPP5F loss in glioma patients is inversely correlated with survival do suggest that the expression of INPP5F might be a positive prognostic factor for glioma patients." (PMID 25476455, 2014). "Based on the fact that INPP5F regulates PI3K-AKT pathway by dephosphorylation and is significantly deregulated in gliomas, we hypothesized that INPP5F might be one of the critical factors in gliomagenesis by regulating PI3K-AKT and its related signaling pathways, such as STAT321." (PMID 25476455, 2014). "Here, we demonstrate that Inositol Polyphosphate-5-Phosphatase F (INPP5F), one of the polyphosphoinositide phosphatases, is differentially expressed in GSCs from glioma patients, and is identified as an inhibitor of STAT3 signaling via interaction with STAT3 and inhibition of its phosphorylation." (PMID 25476455, 2014).
hepatocellular carcinoma (3 papers, 2022 to 2025). A malignant tumor that arises from hepatocytes. "However, the role of INPP5F in hepatocellular carcinoma (HCC) and its underlying mechanisms is unclear." (PMID 34996491, 2022). "Among them, INPP5F has been recently demonstrated to be an oncogene that activates the ASPH-mediated Notch-c-MYC/cyclin E1 pathway in hepatocellular carcinoma." (PMID 37469520, 2023).
diabetes (2 papers, 2016 to 2021). "INPP5F can be used as a negative feedback regulator of insulin signal and downregulation of INPP5F in diabetes mellitus has cardioprotective effect." (PMID 33407475, 2021). "Therapeutically reducing Inpp5f expression or biologically inhibiting its activity would be a promising strategy in protecting cardiac function in the context of diabetes, especially under the context of hyperglycemia and hyperlipidemia." (PMID 26908121, 2016). "To further explore the effects of altered Inpp5f in the context of diabetes, we mainly focused on Akt activity and glucose uptake, the key molecular and cellular readouts of insulin signaling." (PMID 26908121, 2016). "It would be necessary to clarify the function of Inpp5f in diabetes by using Inpp5f transgenic and knockout mice." (PMID 26908121, 2016). "Inpp5f expression correlates well with hyperglycemia and hyperlipidemia in the context of diabetes, and thus inversely correlates with cardiac function." (PMID 26908121, 2016). "We examined the expression of Inpp5f in two established experimental models of diabetes: Type 1 induced by STZ and Type 2 induced by high-fat diet (HFD)." (PMID 26908121, 2016). "Thus, our study has revealed that Inpp5f provides as a negative feedback regulator of insulin signaling and downregulation of Inpp5f in diabetes is cardioprotective." (PMID 26908121, 2016). "However, high blood glucose and lipid, which are characteristics of uncontrolled diabetes and type 2 diabetes, increased Inpp5f expression through activation of NF-κB, blunts the protective feedback." (PMID 26908121, 2016). "In other words, Inpp5f is a potent regulator of Akt activity in the context of diabetes." (PMID 26908121, 2016). "Down-regulation of Inpp5f in response of decreased insulin signaling activity rescues Akt activity in a negative feedback manner and is cardioprotective in the context of diabetes, while uncontrolled hyperglycemia and hyperlipidemia blocks the protective feedback through upregulating Inpp5f." (PMID 26908121, 2016). "In addition, high concentration of glucose and free fatty acid, which are two metabolic stress characteristics of diabetes, also increase Inpp5f expression in an NF-κB dependent manner." (PMID 26908121, 2016). "In this study, we examined the expression of Inpp5f in both STZ- and HFD-induced diabetes mouse model and correlated its expression levels with the blood chemistry parameters and cardiac functional parameters." (PMID 26908121, 2016). "By using the cell culture model, we explored the mechanism how Inpp5f regulates the Insulin/PI3K/PKB/Akt pathway and thus glucose uptake in the context of diabetes." (PMID 26908121, 2016). "Increase of Inpp5f expression at both mRNA and protein levels were observed in HFD induced diabetes model." (PMID 26908121, 2016).
ciliopathy (1 paper, 2012). A genetic disorder of the cellular cilia or the cilia anchoring structures, the basal bodies, or of ciliary function. "In this regard, it is interesting to note that PIP2 phosphatases, INPP5E and INPP5F, are localized in the cilia and their functional deficits are associated with ciliopathy, thus creating a potential gradient of PIP2 physiologically at the cilia-plasma membrane junction." (PMID 23351594, 2012).
Cirrhosis (1 paper, 2022). A chronic disorder of the liver in which liver tissue becomes scarred and is partially replaced by regenerative nodules and fibrotic tissue resulting in loss of liver function. "Further analysis showed that high expression of INPP5F was associated with large tumor size, poor tumor differentiation and cirrhosis." (PMID 34996491, 2022).
Cognitive impairment (1 paper, 2023). Abnormal cognition is characterized by deficits in thinking, reasoning, or remembering. "Downregulation of the Inpp5f gene has been shown to be involved in neuropathic pain and cognitive impairment in rats." (PMID 38248237, 2023).
diabetic cardiomyopathy (1 paper, 2016). Diabetic cardiomyopathy is a disorder of the heart muscle in people with diabetes. "Increased Inpp5f by hyperglycemia and hyperlipidemia is an important mediator of diabetic cardiomyopathy and is a promising therapeutic target for the disease." (PMID 26908121, 2016). "Therapeutic reducing the increased Inpp5f will be a promising way for the treatment of diabetic cardiomyopathy." (PMID 26908121, 2016).
glioblastoma (1 paper, 2014). The most malignant astrocytic tumor (WHO grade IV). "Constitutively expressed INPP5F showed to suppress self-renewal and proliferation potentials of glioblastoma cells and reduced tumorigenicity of glioblastoma." (PMID 25476455, 2014). "Glioblastoma patients with INPP5F deletion (<1.8 copies, 80 cases) have a short survival, significantly different from that with unaltered INPP5F (34 cases), p = 0.0144." (PMID 25476455, 2014). "In 447 glioblastoma samples examined, 385 (86%) exhibited Ch10q25.2-10q26.11 deletion (log2 ratio less than -0.5) and 7 have shown INPP5F gene deletion only." (PMID 25476455, 2014). "Furthermore, the INPP5F expression in patient-derived GSCs and glioblastoma cell lines were analyzed at protein levels and a differently expression pattern of INPP5F protein in these cell lines was observed." (PMID 25476455, 2014). "To identify proteins that interact with INPP5F, we performed co-immunoprecipitation (Co-IP) experiments using anti-V5 with INPP5F overexpressing cells, and found that INPP5F co-precipitated with STAT3 in glioblastoma cell lysates." (PMID 25476455, 2014). "In the present study, we demonstrate that INPP5F strongly inhibits STAT3 activation by interaction with its coiled-coil domain and inhibits its phosphorylation, by which plays essential role in maintaining glioblastoma cells' phenotype and tumorigenic potential." (PMID 25476455, 2014).
Hyperglycemia (1 paper, 2016). An increased concentration of glucose in the blood. "While in the STZ induced diabetic mice, where insulin signal is deficient, Inpp5f is mainly regulated hyperglycemia and hyperlipidemia." (PMID 26908121, 2016). "In contrast, in the STZ mice, Inpp5f is upregulated by hyperglycemia and hyperlipidemia and decreased by low insulin signal." (PMID 26908121, 2016).
primary liver tumor (1 paper, 2019). "The INPP5F gene product negatively regulates the STAT3 signaling pathway by inhibiting phosphorylation of STAT3 but the functional role of the gene in primary liver tumor pathogenesis has not been characterized." (PMID 31796844, 2019).
tumor (7 papers, 2014 to 2025). "Because our above results showed significantly higher INPP5F expression in large HCC tumor cases, we focused on the association between INPP5F and the proliferation ability of HCC cell." (PMID 34996491, 2022). "Given the findings above, we sought to explore the molecular mechanism underlying INPP5F-mediated tumor growth." (PMID 34996491, 2022). "In addition, nuclear-positive staining of INPP5F in adjacent non-tumor tissues was associated with better prognosis in HCC patients." (PMID 34996491, 2022). "The molecular mechanism of INPP5F in regulating tumor growth were studied by transcriptome-sequencing analysis, mass spectrometry analysis, immunoprecipitation assay and immunofluorescence assay." (PMID 34996491, 2022). "When evaluating the IHC staining of INPP5F, we surprisingly found that INPP5F was commonly nuclear-located in cells of adjacent non-tumor tissues, while in tumor tissues, cytoplasmic staining was more common." (PMID 34996491, 2022). "Another interesting finding of our study is the diverse sub-cellular localization of INPP5F between adjacent non-tumor tissues and HCC tissues." (PMID 34996491, 2022). "QRT-PCR and western blot results revealed that mRNA and protein level of INPP5F was frequently upregulated in HCC tissues compared with the corresponding adjacent non-tumor tissues." (PMID 34996491, 2022). "The data strongly supports that INPP5F contributes to inhibition of gliomagenesis as a tumor suppressor." (PMID 25476455, 2014). "Interestingly, INPP5F was commonly nuclear-located in cells of adjacent non-tumor tissues, while in HCC, cytoplasm-located was more common." (PMID 34996491, 2022). "Moreover, TCGA-LIHC cohorts showed that as the tumor status and grade increased, an increased tendency for INPP5F expression is observed." (PMID 34996491, 2022). "The different sub-cellular localization of INPP5F between tumor and adjacent non-tumor tissues in HCC prompted us to hypothesize that cytoplasmic translocation is important for INPP5F to display its oncogenic function." (PMID 34996491, 2022). "Future mechanistic studies may focus on discovering the molecule that regulate the competitive binding of CRM1 and importin-α to INPP5F, making it a more attractive target for anti-tumor therapies." (PMID 34996491, 2022). "Based on this, we hypothesized that INPP5F might act as a tumor suppressor through regulation of oncogenic proteins by phosphorylation inhibition." (PMID 25476455, 2014).
cancer (3 papers, 2018 to 2022). A tumor composed of atypical neoplastic, often pleomorphic cells that invade other tissues. "Recently, INPP5F is also reported to play an important role in the occurrence and progression of malignant tumor, although the role is inconsistent." (PMID 34996491, 2022). "Consistent with the literature, the results of the present study showed fusion of the FGFR2 gene with nine different partners, namely, TACC2, BICC1, BTBD16, WAC, HFM1, HOOK1, INPP5F, C10orf90, and WDR11, in five different types of cancer." (PMID 35342406, 2022). "Meanwhile, NLSs deletion led to cytoplasmic localization of INPP5F, providing an opportunity to bind to ASPH and thereby activate the Notch pathway to exert its cancer-promoting function." (PMID 34996491, 2022).
genetic diseases (1 paper, 2019). "The remaining genes, DPP6, INPP5F, CCHCR1, and CBFA2T3, are also associated with many genetic diseases." (PMID 31332212, 2019).
INPP5F also shares sentences with these, for which no sentence is quoted: chronic lymphocytic leukemia (2 papers); gastric cancer (2); breast carcinoma (1); colon cancer (1); congenital heart disease (1); hyperlipidemia (1); hypertrophic cardiomyopathy (1); melanoma (1); Parkinsonism (1); skin carcinoma (1); type 2 diabetes (1).